NIPA1 (NIPA magnesium transporter 1)
Description:
Acts as a Mg(2+) transporter. Can also transport other divalent cations such as Fe(2+), Sr(2+), Ba(2+), Zn(2+) and Co(2+) but to a much less extent than Mg(2+) (By similarity).
Synonyms: SPG6; MGC35570; SLC57A1; FSP3
Tractability: Antibody: its Gene Ontology location is reachable by antibodies, with high confidence; UniProt places it where antibodies can reach, with medium confidence; UniProt predicts a signal peptide or a membrane-spanning region. PROTAC: its protein half-life has been measured.
Gene: Protein-coding gene on chromosome 15 (22,773,063 to 22,829,789, forward strand). Ensembl gene ENSG00000170113.
Subcellular location: Cell membrane; Early endosome
Pathways (Reactome):
Transport of small molecules: Miscellaneous transport and binding events
Gene Ontology:
Molecular function: protein binding; magnesium ion transmembrane transporter activity
Biological process: magnesium ion transport; transmembrane transport; magnesium ion transmembrane transport
Cellular component: early endosome; membrane; plasma membrane
Genetic constraint (gnomAD): Loss-of-function variants: 6 observed, 14.24 expected, observed/expected ratio (o/e) 0.42, 90% interval 0.23 to 0.83. The upper end of that interval is the gene's LOEUF score, 0.83, which puts it in group 3 of 6, group 1 being the genes least tolerant of losing a copy. Missense variants: 294 observed, 335.33 expected, observed/expected ratio (o/e) 0.88, 90% interval 0.8 to 0.97. Synonymous variants: 195 observed, 161.69 expected, observed/expected ratio (o/e) 1.21, 90% interval 1.07 to 1.36.
Homologues: Orthologues: chimpanzee NIPA1 (99% identical), macaque NIPA1 (99% identical), rat Nipa1 (97% identical), mouse Nipa1 (97% identical), guinea pig NIPA1 (79% identical), rabbit NIPA1 (77% identical), pig NIPA1 (77% identical), tropical clawed frog nipa1 (66% identical), zebrafish nipa1 (54% identical). Paralogues in human: NIPAL1 (42% identical), NIPA2 (41% identical), NIPAL4 (37% identical), NIPAL3 (22% identical), NIPAL2 (19% identical).
Diseases named in the same sentence as NIPA1 in open-access papers:
NIPA1 is named in the same sentence as 44 diseases in open-access papers, as found by Europe PMC text mining. Sharing a sentence is not in itself a finding about the gene and the disease. The quoted sentences say what the papers report.
autism (11 papers, 2012 to 2023). Persistent deficits in social interaction and communication and interaction as well as a markedly restricted repertoire of activity and interest as well as repetitive patterns of behavior. "Similarly there were interesting candidate variants in Patient 6 in NIPA1 gene which has been associated with autism." (PMID 24690944, 2014). "In silico analyses for the four coding genes of NIPA1, NIPA2, CYFIP1, and TUBGCP5 in the 15q11.2 region suggested cardinal disease associations of NIPA1‐Spastic paraplegia 6, NIPA2‐PWS/AS, CYFIP1‐fragile X syndrome and autism, and TUBGCP5‐AS." (PMID 37013615, 2023). "Nine SNPs (rs8025849 in NIPA1, rs3812922 in NIPA2, rs1009153 and rs2289818 in CYFIP1, rs8037745 in SNRPN, rs12438141 and rs1863467 in GABRB3, rs7403021 and rs7180500 in GABRG3) were nominally associated with autism under the recessive model (p < 0.05)." (PMID 30108208, 2018). "Cases VII and VIII present microdeletion of proximal genes (NIPA1, TUBGCP5) and show similar levels of motor and cognitive development, both have mild autism with normal intelligence quotient and motor and language development delay, noted from the first year." (PMID 28174603, 2017).
hereditary spastic paraplegia (8 papers, 2011 to 2025). Hereditary spastic paraplegias (HSP) comprise a genetically and clinically heterogeneous group of neurodegenerative disorders characterized by progressive spasticity and hyperreflexia of the lower limbs. "The loss of chr15:22,760,000–23,080,000 was frequent CNV overlapping a morbid gene NIPA1 associated with hereditary spastic paraplegia." (PMID 38622538, 2024). "Mutations in both SPAST and NIPA1 have been identified as causes of hereditary spastic paraplegia, a condition which causes progressive weakness and spasticity of the legs." (PMID 33562221, 2021). "Dominant mutations in NIPA1 cause hereditary spastic paraplegia." (PMID 21824424, 2011). "The mouse NIPA1 mutants, p.Thr39Arg and p.Gly100Arg, corresponding to the respective human mutants are associated with hereditary spastic paraplegia (HSP) showing a loss-of-function when expressed in oocytes and altered trafficking in transfected COS7 cells." (PMID 32384786, 2020). "Mutations in the human NIPA1 gene cause an autosomal dominant hereditary spastic paraplegia (HSP), a neurodegenerative disorder characterized by progressive lower limb spasticity and weakness." (PMID 30777014, 2019). "In hereditary spastic paraplegia, a neurodegenerative disease characterized by a motor neuron phenotype is thought that NIPA1/SPG6 inhibits BMP signaling by binding to the type II BMP receptor (BMPR2) and promoting its endocytic internalization and degradation." (PMID 35723340, 2022). "The non-imprinted in Prader-Willi/Angelman syndrome 1 (NIPA1) gene has been associated with autosomal dominant hereditary spastic paraplegia 6 (HSP), a progressive neurodegenerative disorder." (PMID 40176798, 2025).
epilepsy (6 papers, 2012 to 2025). A brain disorder characterized by episodes of abnormally increased neuronal discharge resulting in transient episodes of sensory or motor neurological dysfunction, or psychic dysfunction. "NIPA1 is not considered a definitive epilepsy gene, yet has accumulating recent evidence for its association with epilepsy." (PMID 28794409, 2017).
Angelman syndrome (5 papers, 2015 to 2024). A neurogenetic disorder characterized by severe intellectual deficit and distinct facial dysmorphic features. "This region covered the TUBGCP5, CFYIP1, NIPA1 and NIPA2 genes, which were critical genes causing behavioral and academic differences in the Prader-Willi/Angelman syndrome." (PMID 38784233, 2024). "The less frequent microdeletion 15q11.2, containing four protein-coding genes (NIPA1, NIPA2, CYFIP1, and TUBGCP5), is associated with Burnside–Butler syndrome (BBS), which partially overlaps with certain neurodevelopmental disorders, including Prader-Willi and Angelman syndrome." (PMID 36553064, 2022). "It is adjacent to the Parder–William/Angelman syndrome imprinting area, and its size is approximately 500 kb, involving four OMIM genes: NIPA1, NIPA2, CYFIP1, and TUBGCP5, which are hot spots in clinical research." (PMID 38172840, 2024).
Spastic paraplegia (5 papers, 2009 to 2023). Complete loss of the ability to move the lower limbs accompanied by spasticity of the lower limbs. "Of the genes in this region, certain pathogenic variants in the NIPA1 gene causes an autosomal dominant form of spastic paraplegia and triplet repeat expansion within this gene is associated with a higher risk for amyotrophic lateral sclerosis." (PMID 30909440, 2019).
developmental delay (4 papers, 2020 to 2025). "The copy number variation (CNV) of 15q11.2, an emerging and common condition observed during prenatal counseling, is encompassed by four highly conserved and non-imprinted genes—TUBGCP5, CYFIP1, NIPA1, and NIPA2—which are reportedly related to developmental delays or general behavioral problems." (PMID 34680874, 2021).
Intellectual disability (4 papers, 2020 to 2023). "A rare NIPA1 deletion was also found in a patient with pervasive developmental disorder not otherwise specified and with mild intellectual disability; this deletion is also linked to autism (SFARI.org)." (PMID 32384786, 2020). "Both proband 15, a boy affected by TS, OCD, behavioral problems, and mild dysmorphic features, and proband 19, a girl affected by TS, mild intellectual disability, and ODD, presented the recurrent 15q11.2 deletion of about 395 Kb, which includes TUBGCP5, CYFIP1, NIPA1, and NIPA2 genes." (PMID 36833427, 2023). "Copy number variations in NIPA1 were found in psychiatric disorders, KIAA1211L was identified in a schizophrenia twin-study and is a candidate gene for opioid abuse, and AFF3 is involved in intellectual disability and cellular migration in the cerebral cortex of mice." (PMID 33004014, 2020).
autosomal dominant spastic paraplegia (3 papers, 2014 to 2020). "However, mutations in the NIPA1 gene have been reported previously in autosomal dominant spastic paraplegia." (PMID 24778887, 2014).
schizophrenia (3 papers, 2018 to 2020). A major psychotic disorder characterized by abnormalities in the perception or expression of reality. "Moreover, mutations in each gene were associated with different disorders: NIPA1 with autosomal-dominant hereditary spastic paraplegia, NIPA2 with childhood absence epilepsy, TUBGCP5 with ADHD and obsessive-compulsive disorder, and CYFIP1 with increasing susceptibility to ASD and with schizophrenia." (PMID 30583851, 2019).
amyotrophic lateral sclerosis (2 papers, 2019 to 2024). Amyotrophic lateral sclerosis (ALS) is a neurodegenerative disease characterized by progressive muscular paralysis reflecting degeneration of motor neurons in the primary motor cortex, corticospinal tracts, brainstem and spinal cord. "For example, specific missense variants of the NIPA1 (non-imprinted in PWS/AS 1; OMIM # 608145) gene are known to cause autosomal dominant hereditary spastic paraplegia and postural disturbance; repeat expansions have recently been associated with amyotrophic lateral sclerosis." (PMID 30909440, 2019).
Anxiety (1 paper, 2023). Intense feelings of nervousness, tension, or panic often arise in response to interpersonal stresses. "NIPA1 duplication, associated with anxiety, is among the top genes of DD." (PMID 37486921, 2023).
dementia (1 paper, 2021). Loss of intellectual abilities interfering with an individual's social and occupational functions. "One example of a region with conflicting reports overlaps CYFIP1 and NIPA1 where we observed duplications in two Turkish dementia patients." (PMID 34321086, 2021). "Our candidate CNVs overlapping both CYFIP1 and NIPA1 were predicted as likely benign by ClassifyCNV, and we did not observe a significant association with such CNVs and dementia in the UKBB." (PMID 34321086, 2021).
hereditary spastic paraplegia type 6 (1 paper, 2022). "Mutations in the non-imprinted in Prader-Willi/Angelman syndrom 1 (NIPA1) gene have been identified as the cause of hereditary spastic paraplegia type 6 (SPG6) with an autosomal dominant (AD) mode of inheritance." (PMID 35464835, 2022).
neurodegenerative disease (3 papers, 2022 to 2023). A disorder of the central nervous system characterized by gradual and progressive loss of neural tissue and neurologic function. "We also observed SLC15A1, a peptide transporter protein associated with digestion and absorption, on chromosome 13 and a positive selection signal for the NIPA1 gene, which causes neurodegenerative diseases in chromosome 15." (PMID 36721228, 2023). "Downregulation of ANG, VEGFA, SURF4, and NIPA1 suggests impacts on neurodegenerative diseases and metabolic disorders." (PMID 38681774, 2023). "SURF4 affects insulin secretion, and reductions in NIPA1 are tied to neurodegenerative diseases." (PMID 38681774, 2023).
neurodevelopmental disorder (3 papers, 2012 to 2022). A behavioral and cognitive disorder with onset during the developmental period that involves impaired or aberrant development of intellectual, motor, or social functions. "In this study, we explored functions and interactions of the four protein-coding genes in this region, namely NIPA1, NIPA2, CYFIP1, and TUBGCP5, and elucidate their role, in solo and in concert, in the causation of neurodevelopmental disorders." (PMID 32384786, 2020).
brain disorder (1 paper, 2021). A disease affecting the brain or part of the brain. "In addition, three of the four genes (CYFIP1, NIPA1, and NIPA2) have been shown to play a role in neurodevelopment and are associated with brain disorders." (PMID 34970295, 2021).
cancer (1 paper, 2024). A tumor composed of atypical neoplastic, often pleomorphic cells that invade other tissues. "Studies have shown that the expression of MAGT1 impacted the progression of cancer, and NIPA1 and NIPAL1 were related with poor prognosis." (PMID 39242581, 2024). "For example, NIPA1 and NIPAL1 were related with poor prognosis of cancers, and MAGT1 knockdown inhibited tumor progression." (PMID 39242581, 2024).
NIPA1 also shares sentences with these, for which no sentence is quoted: Ataxia (2 papers); attention deficit-hyperactivity disorder (2); autism spectrum disorder (2); fragile X syndrome (2); obsessive-compulsive disorder (2); psychiatric disorder (2); acute myeloid leukemia (1); anorexia nervosa (1); autosomal dominant spastic paraplegia 3A (1); autosomal dominant spastic paraplegia 4 (1); Cerebellar atrophy (1); childhood absence epilepsy (1); congenital heart disease (1); Dyscalculia (1); dyslexia (1); frontotemporal dementia (1); metabolic disorders (1); neurological diseases (1); Obesity (1); paraplegia (1); Parkinson disease (1); pervasive developmental disorder - not otherwise specified (1); Prader-Willi syndrome (1); psychosis (1); Spastic paraplegia 6 (1); Troyer syndrome (1); tumor (1).